GDF11 (growth differentiation factor 11)
Diseases named in the same sentence as GDF11 in open-access papers (continued):
Sharing a sentence is not in itself a finding about the gene and the disease.
cardiovascular disease (16 papers, 2016 to 2025). "Growth Differentiation Factor 11 (GDF11) is a member of transforming growth factor β (TGF‐β) superfamily associated with cardiovascular diseases." (PMID 33764670, 2021). "In the field of cardiovascular diseases, some studies suggest that GDF11 decreases the risk of cardiovascular events and death in patients with stable ischaemic heart disease and improves aging-related cardiac hypertrophy." (PMID 29113418, 2017). "However, increased GDF11 was found to be a risk factor for frailty and cardiovascular disease, demonstrating that exogenous GDF11 induces skeletal and cardiac muscle decline in mice." (PMID 37830636, 2023). "However, the research of quantification of GDF11 in human aging and cardiovascular disease indicated that individuals with higher GDF11 were more likely to be frail, and higher GDF11 at surgical baseline was associated with rehospitalization and multiple adverse events." (PMID 33728018, 2021). "Numerous studies have consistently demonstrated that GDF11 plays a significant role in pyroptosis and the treatment of cardiovascular disease." (PMID 38715043, 2024). "In this review, we described the gene structure and signaling pathways of GDF11, as well as the roles of GDF11 in organ development, aging, cardiovascular disease, neurological disease, and other diseases." (PMID 33886503, 2021). "As a fact, the role of GDF11 in ageing, cardiovascular diseases and function of ECs is still not fully understood, or sometimes controversial." (PMID 32588524, 2020). "A large number of studies have confirmed that GDF11 is widely used in the process of pyroptosis and treatment of cardiovascular disease, respectively." (PMID 33100331, 2020). "Therefore, as a protective factor for cardiovascular diseases, GDF11 can play a positive role in improving vascular remodeling." (PMID 35033112, 2022). "This has led to a debate on the role of GDF11 in aging and cardiovascular diseases." (PMID 29113418, 2017). "Therefore, GDF11 may be beneficial and serve as a promising therapeutic rejuvenation factor in age-related cardiovascular disease when its levels are appropriate." (PMID 33886503, 2021). "Another report suggested that higher GDF11/myostatin circulating levels were associated with a lower risk of cardiovascular events and death, and a separate study demonstrated that GDF11 did not decline with age and was associated with a higher risk of cardiovascular diseases." (PMID 29783655, 2018). "However, other studies concluded that GDF11 was associated with comorbidity, frailty, and post-operative outcomes in cardiovascular disease and that GDF11 supplementation did not rescue aging-related pathological hypertrophy." (PMID 29113418, 2017). "A previous study analyzing the levels of GDF11 in human T2D found increased levels of GDF11 only in T2D patients with cardiovascular disease, but not in T2D patients free of cardiovascular problems." (PMID 30897065, 2019). "However, the role of GDF11 in aging and cardiovascular diseases is controversial and not comprehensively studied." (PMID 29113418, 2017).
metabolic disorders (9 papers, 2019 to 2024). "In particular, overexpression of SERPINE1 and downregulation of ID1 genes, known to be associated with metabolic disorders, could represent other intracellular downstream mediators of GDF11 effects." (PMID 35920128, 2022). "GDF11 is a member of the TGF‐β superfamily that was recently implicated as potential “rejuvenating” factor, which can ameliorate metabolic disorders." (PMID 35920128, 2022). "A deep understanding of the role of GDF11 in metabolically active tissues and immune cell types would likely open opportunities to develop new safe therapeutics for metabolic disorders." (PMID 33126224, 2020). "The second possibility is that GDF11 blocks pathways that lead to metabolic disorders that involve inflammatory cytokines and activation of macrophages." (PMID 31847906, 2019). "GDF11 function demonstrated here would suggest a potential use of GDF11 by gene transfer for the treatment of metabolic diseases." (PMID 31847906, 2019). "As such, GDF11 could be considered as an important therapeutic candidate for age‐related neurodegenerative and metabolic disorders." (PMID 31637864, 2020). "These outcomes suggest that GDF11 may be effective in the treatment of metabolic diseases." (PMID 33886503, 2021). "Regarding the impact of the GDF11 molecule in various metabolic pathways GDF11 is a promising target for the prevention and treatment of MAFLD and other metabolic disorders in the future." (PMID 38494851, 2024). "Moreover, since adiponectin has multiple antidiabetic, anti‐atherogenic effects, it would be crucial to explore whether a synergistic administration of GDF11 and adiponectin would further enhance the beneficial effects of this treatment in age‐related and metabolic disorders." (PMID 31637864, 2020).
neurodegenerative disease (5 papers, 2013 to 2024). A disorder of the central nervous system characterized by gradual and progressive loss of neural tissue and neurologic function. "Positive correlations between vitamin D, HDL, and GDF11 have shown the protective effect of vitamin D in relation to, e.g., cardiovascular or neurodegenerative diseases." (PMID 38275413, 2024). "GDF11 enhances the neurovascular disease as well as neurodegenerative disease, while it also enlarges the volume of the skeletal muscle and further improves the muscular strength." (PMID 35783640, 2022). "The identification of GDF11 as a “rejuvenating factor” opens up perspectives for the treatment of neurodegenerative diseases." (PMID 31330871, 2019). "Taking into consideration anti-ageing properties of GDF11, it would be intriguing to apply this study design to individuals within different age groups as well as in those already diagnosed with an early phase neurodegenerative disease." (PMID 37033257, 2023). "Consistent with these properties, GDF11 treatment may protect the brain, and its administration may be a viable approach for improving deleterious aspects of brain aging and neurodegenerative diseases." (PMID 31330871, 2019). "By analogy with myostatin and muscle regeneration, anti-GDF11 therapy might be of value in neurodegenerative disease; however we still require an in-depth knowledge of how this growth factor regulates neural stem cell function." (PMID 24244313, 2013).
cardiac diseases (4 papers, 2017 to 2023). "Exploration of the Gnomad database suggests that mutations in GDF11 are infrequent (pLOF: pLI = 0.98 o/e = 0.06), but mutations in GDF11 are associated with cardiac diseases (HuGE score: 4.28)." (PMID 38235060, 2023). "Recently, a prospective cohort study also revealed that higher levels of GDF11/8 were associated with lower risk of cardiovascular events and death in patients with stable ischaemic heart disease." (PMID 30202652, 2018). "GDF11 decreases the risk of cardiovascular events and death in patients with stable ischaemic heart disease, protects against endothelial injury and reduces atherosclerotic lesion formation in apolipoprotein E-Null mice." (PMID 29113418, 2017).
adenocarcinoma (3 papers, 2019 to 2024). A common cancer characterized by the presence of malignant glandular cells. "Interestingly, despite the higher grading (G3) observed in adenocarcinomas, it was associated with lower GDF11 expressions." (PMID 38611614, 2024).
liver (2 papers, 2020 to 2024). "GDF11-treated mice showed mildly exacerbated hepatic collagen deposition, accompanied by weight loss and without changes in liver steatosis or inflammation." (PMID 33126224, 2020).
neurological disease (2 papers, 2021 to 2023).
genetic diseases (1 paper, 2023). "In addition, the biology of GDF11 is clearly relevant to humans given new reports of GDF11 loss-of-function genetic diseases that can affect the cardiovascular system, musculoskeletal, and nervous systems." (PMID 38235060, 2023).
infection (1 paper, 2021). The state of being infected such as from the introduction of a foreign agent such as serum, vaccine, antigenic substance or organism. "For in vivo infection, we employed multipoint myocardial injection of adenoviruses to overexpress and knockdown GDF11 in the heart, which prevented GDF11 from impacting other organs, such as liver, spleen, lung, kidney, and skeletal muscle." (PMID 34215721, 2021).
neurodevelopmental disorder (1 paper, 2023). A behavioral and cognitive disorder with onset during the developmental period that involves impaired or aberrant development of intellectual, motor, or social functions.
neuromuscular disease (1 paper, 2017). "Serum concentrations of myostatin (MSTN or GDF8), follistatin (FSTN), GDF11 and ACTIVIN A were determined in patients affected by several neuromuscular diseases with various levels of muscle atrophy and in controls." (PMID 29192144, 2017).
GDF11 also shares sentences with these, for which no sentence is quoted: type 2 diabetes (6 papers); intracerebral hemorrhage (4); acute myocardial infarction (3); acute pancreatitis (2); Anxiety (2); chronic heart failure (2); esophageal cancer (2); fatty liver (2); Glucose intolerance (2); age (1); anorexia nervosa (1); Arrhythmia (1); cataract (1); Cirrhosis (1); cognitive disorder (1); Duchenne muscular dystrophy (1); erythroleukemia (1); female infertility (1); hypertrophic cardiomyopathy (1); inflammatory skin disease (1); kidney injury (1); Left ventricular dilatation (1); memory impairment (1); muscle atrophy (1); neurotoxicity (1); non-alcoholic steatohepatitis (1); pancreatitis (1); psychosis (1); respiratory disease (1); spinal cord injury (1).
A further 4 diseases each share a sentence with GDF11 in 1 paper.